RTP4 (receptor transporter protein 4)
Description:
Chaperone protein that facilitates the trafficking and functional cell surface expression of some G protein-coupled receptors (GPCRs). Promotes functional expression of the bitter taste receptor TAS2R16. Also promotes functional expression of the opioid receptor heterodimer OPRD1-OPRM1 (By similarity). In addition, acts as a potent IFN-inducible suppressor of pathogens including lyssavirus rabies, influenza A or yellow fever virus. Mechanistically, associates with the viral replicase, binds viral RNA, and thereby suppresses viral genome amplification that replicates at the endoplasmic reticulum (By similarity). In addition, restores antiviral signaling by interacting with and sequestering influenza A virus protein NS1.
Synonyms: IFRG28; Z3CXXC4
Tractability: Antibody: UniProt predicts a signal peptide or a membrane-spanning region. PROTAC: ubiquitination databases record sites on it.
Gene: Protein-coding gene on chromosome 3 (187,368,385 to 187,372,076, forward strand). Ensembl gene ENSG00000136514.
Subcellular location: Membrane; Cytoplasm
Subcellular location (Human Protein Atlas): Nucleoplasm
Gene Ontology:
Molecular function: protein binding; olfactory receptor binding
Biological process: defense response to virus; detection of chemical stimulus involved in sensory perception of bitter taste; protein targeting to membrane; protein insertion into membrane
Cellular component: cytoplasm; nucleoplasm; membrane
Genetic constraint (gnomAD): Loss-of-function variants: 3 observed, 6.59 expected, observed/expected ratio (o/e) 0.46, 90% interval 0.21 to 1.17. That is too few expected variants to judge how well the gene tolerates losing a copy. Missense variants: 266 observed, 305.18 expected, observed/expected ratio (o/e) 0.87, 90% interval 0.79 to 0.96. Synonymous variants: 112 observed, 122.18 expected, observed/expected ratio (o/e) 0.92, 90% interval 0.79 to 1.07.
Homologues: Orthologues: macaque RTP4 (92% identical), chimpanzee RTP4 (87% identical), dog RTP4 (55% identical), mouse Rtp4 (43% identical), rat Rtp4 (41% identical). Paralogues in human: RTP3 (36% identical), RTP2 (26% identical), RTP1 (25% identical), RTP5 (23% identical).
Diseases named in the same sentence as RTP4 in open-access papers:
RTP4 is named in the same sentence as 41 diseases in open-access papers, as found by Europe PMC text mining. Sharing a sentence is not in itself a finding about the gene and the disease. The quoted sentences say what the papers report.
viral infection (8 papers, 2017 to 2025). "Several reports have implicated RTP4 as playing a role in the innate immune response to virus infection." (PMID 37382452, 2023). "Whereas prior studies leveraged a variety of truncation and point-mutated versions of paRTP4 and hsRTP4, our study presents an analysis of interspecies domain-swap chimeric versions of RTP4 in the context of viral infection." (PMID 40920810, 2025). "The initial defense and adaptive immune responses against viral infection are performed by type I IFNs (IFN-α/β) such as RTP4, GBP1, OAS1, IFI27, and IF44L." (PMID 31665046, 2019). "An increasing number of studies indicate that RTP4 can serve as one of the important markers of diagnosis or prognosis of various diseases, such as cutaneous melanoma, breast cancer, type 2 diabetes and viral infection." (PMID 36291680, 2022).
cutaneous melanoma (4 papers, 2021 to 2025). A primary melanoma arising from atypical melanocytes in the skin. "Variants of RTP4 have additionally been implicated in diseases ranging from primary Sjogren’s syndrome to cutaneous melanoma, and it has been demonstrated to have a pro-inflammatory effect in neuroinvasive infections." (PMID 40920810, 2025). "RTP4 is a novel prognosis-related hub gene in cutaneous melanoma." (PMID 34154655, 2021).
melanoma (4 papers, 2021 to 2025). A malignant, usually aggressive tumor composed of atypical, neoplastic melanocytes. "We further discovered that RTP4 was associated with immune cell infiltration, which negatively correlated with the cellular purity of melanomas and positively correlated with neutrophils." (PMID 34154655, 2021). "As a result, we discovered that RTP4 was associated with immune cell infiltration of melanoma metastases." (PMID 34154655, 2021). "We discovered that RTP4 was associated with immune cell infiltration of samples of melanoma metastases, which negatively correlated with the cellular purity of melanomas and positively correlated with neutrophils." (PMID 34154655, 2021). "RTP4 was significantly associated with the prognosis of patients with melanoma and was defined as a prognostic gene." (PMID 34154655, 2021). "Previous literature showed that the Rtp4 expression in melanoma tissue was significantly positively correlated with neutrophil infiltration, and higher Rtp4 expression foreshadowed longer overall survival of melanoma patients." (PMID 40090940, 2025). "The novel gene RTP4 identified here will facilitate the exploration of the molecular mechanism of the pathogenesis and progression of melanoma and the discovery of potential new target for drug therapy." (PMID 34154655, 2021). "Log-rank analysis and multivariate Cox model analysis identified 13 genes that were associated with the prognosis of the metastatic melanoma group, and RTP4 was validated as a prognostic gene using two independent melanoma datasets." (PMID 34154655, 2021). "RTP4 has also been reported that it is significantly associated with immune cell infiltration and immune checkpoint encoding genes (PDCD1, TIM-3, and LAG3) in melanoma." (PMID 37152371, 2023). "RTP4 expression negatively correlated with melanoma purity and highly correlated with neutrophils." (PMID 34154655, 2021). "To determine whether the immune-related gene RTP4 expressed by patients with melanoma had predicted drug targets, we queried the ChEMBL and Drugbank databases." (PMID 34154655, 2021). "We further discovered that PDCD1, CTLA4, TIM-3, LAG3, and RTP4 were upregulated in melanomas." (PMID 34154655, 2021). "The immunohistochemical images of IFNGR2, CCL25, IL15, RTP4, and NLRP6 in both normal skin tissue and melanoma tissue confirmed the expression of the GRIPs in CM." (PMID 35492358, 2022). "Notably, RTP4 is a novel gene not previously associated with melanoma." (PMID 34154655, 2021).
breast carcinoma (3 papers, 2021 to 2023). "The expression level of receptor transporter protein 4 (RTP4) can be used to independently predict the outcome of breast cancer in HER2 (+) patients, and its high expression level is associated with poor survival and prognosis." (PMID 34384424, 2021). "In previous studies, RTP4 was shown to regulates prostate cancer via methylation and is regarded as a precise target, whose expression levels can be used to independently predict the prognosis of HER2(+) breast cancer." (PMID 37396042, 2023).
COVID-19 (3 papers, 2021 to 2024). A disease caused by infection with severe acute respiratory syndrome coronavirus 2. "Several IFN-related genes, such as SPATS2L, OAS2, ISG15, ZBP1, and IFI44L, exhibited similar patterns of upregulation across both dengue and COVID-19 datasets, while others, such as AIM2 and RTP4, showed distinct regulation." (PMID 38444851, 2024).
parasite infection (3 papers, 2020 to 2023). "Other studies have shown that the RTP4 was overexpressed in some connective tissue disorders and parasitic infections and correlated with some cancers." (PMID 37152371, 2023). "Su’s group has suggested that the IFN-I and IFN-I pathways can induce RTP4 expression after parasite infection." (PMID 33363057, 2020). "Inhibition of RTP4 expression may help lower parasitemia and be beneficial to alleviate symptoms of cerebral malaria (CM) and other neuropathology." (PMID 36825026, 2023). "Inhibition of RTP4 expression may help reduce parasitemia and help to alleviate symptoms of cerebral malaria (CM) and other diseases with neuropathology." (PMID 33363057, 2020).
prostate carcinoma (3 papers, 2019 to 2023). A carcinoma that arises from epithelial cells of the prostate gland. "Recent studies have shown that the methylation center gene RTP4 in prostate adenocarcinoma can be regarded as a biomarker for the diagnosis and treatment of prostate cancer." (PMID 34384424, 2021).
primary Sjogren’s syndrome (2 papers, 2022 to 2025). "A genome-wide association study (GWAS) of patients with Sjögren’s syndrome identified an association with genetic variants of the RTP4 gene influencing the severity of fatigue." (PMID 35508622, 2022).
tuberculosis (2 papers, 2023 to 2024). A chronic, recurrent infection caused by the bacterium Mycobacterium tuberculosis. "To conclude, our results suggest that RTP4 can be used as a biomarker to identify tuberculosis infection, providing a new perspective on TB diagnosis in clinical." (PMID 37152371, 2023).
allergic asthma (1 paper, 2024). A asthma with a basis in a pathological type I hypersensitivity reaction. "Although the precise role of RTP4 in the inflammatory mechanism has not been fully elucidated, the observation that RTP4 is upregulated in peripheral tissues under various inflammatory conditions, such as colitis and allergic asthma, suggests its physiological significance in inflammatory processes." (PMID 39769444, 2024).
colorectal cancer (1 paper, 2025). A primary or metastatic malignant neoplasm that affects the colon or rectum. "While RTP4 is known to regulate odorant receptor trafficking, its role in colorectal cancer (CRC) remains unclear." (PMID 41126439, 2025).
Hypertension (1 paper, 2016). The presence of chronic increased pressure in the systemic arterial system. "This analysis allowed us to identify 6 well-annotated genes: RTP4, FXYD6, GDF11, IFNAR1, NOX3, and HLA-DQ2, associated with dynamics of future hypertension incidence." (PMID 27980621, 2016).
lupus nephritis (1 paper, 2022). Glomerulonephritis in the context of systemic lupus erythematosus. "Receptor transporter protein 4 (RTP4) is associated with lupus nephritis." (PMID 36405750, 2022).
metastatic carcinoma (1 paper, 2023). A carcinoma which has spread from the original site of growth to another anatomic site. "It was found that RTP4, SERTAD2, and SP110 were significantly expressed in all pancreatic cancer cells, including those of pancreatic ductal carcinoma, pancreatic adenocarcinoma and metastatic carcinoma, providing a reliable basis for subsequent elucidation of pancreatic cancer pathogenesis." (PMID 37396042, 2023).
metastatic melanoma (1 paper, 2021). A melanoma that has spread from its primary site to another anatomic site. "RTP4 has the potential to be an effective biomarkers and therapeutic targets in metastatic melanoma." (PMID 34154655, 2021). "Above results demonstrated that patients with metastatic melanoma with high expression of RTP4 experienced significantly longer overall survival than those with low expression." (PMID 34154655, 2021).
pulmonary tuberculosis (1 paper, 2023). A bacterial infection that affects the lungs and is caused by Mycobacterium tuberculosis. "RTP4 was significantly upregulated in the pulmonary tuberculosis group compared to the healthy control group in three gene sets and downregulated after antituberculosis therapy in one gene set." (PMID 37152371, 2023). "RTP4 might be a new potential biomarker for diagnosing pulmonary tuberculosis." (PMID 37152371, 2023).
Q fever (1 paper, 2014). A bacterial infection caused by Coxiella burnetii. "Most of the early genes were found to be up-regulated in monocytes from patients with acute Q fever, two of them, NLRC5 and RTP4, were up-regulated by IFN-γ, suggesting that IFN-γ plays a role in the host response during acute Q fever." (PMID 25346736, 2014).
sarcoidosis (1 paper, 2022). Sarcoidosis is a multisystemic disorder of unknown cause characterized by the formation of immune granulomas in involved organs. "In addition, we found that LRRN3, IFI44, LHFPL2, RTP4, and EPHX2 were all involved in diagnosing sarcoidosis, which might shed light on the mechanisms of sarcoidosis and provide potential biomarkers for diagnosis." (PMID 36405616, 2022).
steatosis (1 paper, 2024). Increased lipid within the cytoplasm of cells. "Similarly, RTP4 is significantly upregulated in NASH in five datasets as well as in steatosis in one of the GEO entries (adj." (PMID 39562169, 2024).
infection (13 papers, 2019 to 2025). The state of being infected such as from the introduction of a foreign agent such as serum, vaccine, antigenic substance or organism. "While murine RTP4 exerts divergent effects in the contexts of flavivirus (antiviral) and nidovirus (agnostic) infections, it is possible that it plays a role in rendering mice impermissible to other human-tropic pathogens." (PMID 40920810, 2025). "Anatomically, RTP4 was found to play important roles in peripheral immune cells, such as macrophages, in response to infections." (PMID 39769444, 2024). "Many negative regulators, such as Tetherin, NLRC5, NLRP11, and RTP4, are induced after infection, to feedback and inhibit the production of IFNs." (PMID 37366613, 2023). "One X. laevis RTP, RTPγS, inhibits viral replication and directly binds viral RNA during infection, which is similar to the antiviral mechanism of mammalian RTP4." (PMID 34014925, 2021). "RTP4 is both an antiviral effector that restricts infection by RNA viruses of the family Flaviviridae and a negative regulator of TBK1-mediated signaling pathways." (PMID 34014925, 2021). "We previously found that mammalian RTP4 is a rapidly evolving antiviral effector which inhibits infection by RNA viruses from the family Flaviviridae." (PMID 34014925, 2021). "Given the established dsRNA-binding capability of human and black flying fox RTP4 in other infections, steric hindrance is a likely hypothesis for the conserved mechanism of HCV inhibition by RTP4, viperin, and CH25H." (PMID 40920810, 2025). "Indeed, by in situ proximity ligation, we found that mmRTP4 directly associates with the HCV NS5A protein significantly more than human RTP4 during infection." (PMID 40920810, 2025). "The induction levels of antiviral genes—including DDX58, OAS1, OAS2, ISG15, MX2, IFI44L, RTP4, and IFNB1—were markedly reduced in KO cells compared to WT cells post-infection." (PMID 40872812, 2025). "We found a significant temporal induction of ISGs (for example, MX1, RTP4, IRF7, USP18, TRANK1) in alvORG at day 3 after infection compared to mock-infected samples or nasalALI at day 5 and day 7 compared to day 1 after infection." (PMID 40399606, 2025). "The 17 DEGs upregulated after infection with huH1N1 were shared with the swH1N1 infection (DDX58 (RIG-I), RSAD2 (Viperin), MX2, MX1, OAS1, ANGPTL4, IRF7, ISG15, IFIT1, ISG12(A), DDX60, BST2, IFI44, XAF1, LGALS3BP, RTP4, and IFI6)." (PMID 39247193, 2024). "Additionally, RTP4 may contribute to the suppression of type I IFN induction during the cyclic GMP-AMP synthase (cGAS)-stimulator of interferon genes (STING) pathway following pathogen infection, functioning as a negative regulator." (PMID 39769444, 2024). "We further detected 28 of the ISG expression levels upon H37Rv infection at multiplicities of infection 2 (MOI = 2) for 6, 24, and 48 h and approximately 90% (25 out of 28) of the ISGs (except for LY6E, RTP4, and TREX1) were significantly increased in hMDMs." (PMID 30717477, 2019). "We found that, in addition to a broad induction of ISGs (for example, DTX3L, OAS3, RTP4, IRF7, MX2, IFIT3, IFIH1), only IFNB1 and, more robustly, IFNL1-like and IFNL3-like were induced in virus-infected organoids at 1 and 3 days after infection compared to the uninfected controls." (PMID 40399606, 2025). "However, in response to infection, male mice exhibited higher expression levels of CXCL2 (KO, 1A3, and 6A2), SAMHD1 (1A0, 1A3), RSAD2, STAT1, and STAT3 (1A0), MYD88 and PSMB8 (1A3), BCL3, BCL10, CCRL2, IFITM2, RTP4, and ZFP36L1 (6A2), compared to females." (PMID 32670284, 2020).
cancer (6 papers, 2019 to 2023). A tumor composed of atypical neoplastic, often pleomorphic cells that invade other tissues. "Several studies have found that RTP4 is strongly linked to a virus defense response and cancer prognosis." (PMID 36845395, 2023). "Interestingly, most of these genes are linked with cancer processes (Pld1, Fam13c, Svbp, TMem192, Zc3h7a, RTP4, Naa30, Zgrf1, Slc33a1, Dnmt3b, Map6, Plin4, Eps8L2, Alg12, Capg and Tdp2)." (PMID 37700325, 2023). "The results of pan-cancer analysis showed that high expression of RTP4 in 4 tumor types was positively correlated with poor prognosis and high expression of RTP4 in 6 tumor types was negatively correlated with poor prognosis." (PMID 37152371, 2023). "To further explore the relationship between the expression of RTP4 and tumors, we performed a pan-cancer analysis based on TCGA database." (PMID 37152371, 2023). "Further, RTP4 is required for antigen-dependent immune editing of cancer cells using CRISPR screens." (PMID 34154655, 2021). "RTP4 represents a novel targeting opportunity for many kinds of cancers." (PMID 34154655, 2021).
tumor (6 papers, 2020 to 2025). "RTP4 expression showed strong associations with immune-related genes, biological processes and anti-tumour immune cell infiltration." (PMID 41126439, 2025). "It was also found that RTP4 expression was different between some tumor and normal tissues, and it was correlated with the overall survival time and stage of some tumors." (PMID 37152371, 2023). "After exploring the expression difference of the RTP4 gene in different clinical stages in each type of tumor, we found significant differences among the 5 types of tumors." (PMID 37152371, 2023). "Furthermore, the ROC curve analysis showed that hub gene (CXCL8, DDX60, IFI44L, RSAD2, and RTP4) could distinguish OC from normal tissues, and the diagnosis effect of tumor tissue was better, and the combined diagnosis of five genes was the best." (PMID 34384424, 2021). "Mechanistic studies demonstrated that RTP4 upregulates MHC-I expression, which enhances CD8+ T cell recruitment and strengthens anti-tumour immunity in both cellular and animal models." (PMID 41126439, 2025). "M1 macrophage-related genes include IL-6, IL-8, CD80, PIM1, RTP4, and SLC11A1, and studies have shown that after metformin treatment, the expression of M1-related factors in tumor cells can be enhanced or weakened, thus affecting the prognosis of the tumor." (PMID 33193731, 2020).
RTP4 also shares sentences with these, for which no sentence is quoted: influenza (2 papers); atherosclerosis (1); bacterial infection (1); bacterial pneumonia (1); cognitive decline (1); colitis (1); colon cancers (1); connective tissue disorder (1); dengue (1); hepatocellular carcinoma (1); malaria (1); Obesity (1); pancreatic adenocarcinoma (1); pancreatic cancer (1); pancreatic ductal carcinoma (1); papilloma (1); prostate adenocarcinoma (1); toxoplasmosis (1); type 2 diabetes (1).